MMP9 (matrix metallopeptidase 9)
Diseases named in the same sentence as MMP9 in open-access papers (continued):
Sharing a sentence is not in itself a finding about the gene and the disease.
tumor (continued). "The sparseness of the data precluded the possibility of performing a multivariate analysis in order to examine the combination of MMP-9 with the other two clinical factors (tumor stage and nodal status) that were significantly associated with recurrence-free survival in univariate Cox analysis." (PMID 22410369, 2012). "Besides, many studies have also linked the activity of PI3K-AKT and ERK pathways to MMP-9 expression in other tumor cell lines." (PMID 21738655, 2011). "Moreover, it is well known that production of MMP-2 and MMP-9 in PCa cells is associated to tumor invasion and progression." (PMID 21489246, 2011). "Tumor-associated neutrophils are a major source of MMP9 (along with macrophages and mast cells) in various murine tumor models and so could promote angiogensis by releasing potent angiogenic factors such as VEGF that are usually sequestered in the ECM." (PMID 20490273, 2010). "As increased production of MMP2 and MMP9 is associated with tumour invasion, we examined the capacity of G3F cells to produce the enzymes that are implicated in the breakdown of basement membrane by invading tumour cells." (PMID 20197768, 2010). "Similarly, in patients with breast cancer, increased serum and tissue expression of MMP9 was associated with a worse prognosis of the course of tumor." (PMID 20037727, 2009). "Molecular-genetic studies of the functional −1562 C/T polymorphism of the MMP9 gene have revealed a frequent association of T allele with an increased risk of some kinds of cancer and with more severe progression of the tumor and/or greater dynamics of metastases." (PMID 20037727, 2009). "CD44 is shown to associate with a proteolytic form of MMP-9 on the surface of various tumor cells." (PMID 19290049, 2009). "Extreme tumour MMP-9 levels were associated with poor prognosis but SNP MMP-9−1562C>T was not." (PMID 18506186, 2008). "Thus, loss of MT1-MMP consistently decreased the invasion or growth promoting influence of fibroblasts in vivo and in vitro and loss of MMP-2 and MMP-9 altered tumor growth with increasing complexity of the model system." (PMID 16515711, 2006). "A low urinary MMP9 : TIMP1 ratio was also shown to indicate an increased risk of tumour recurrence." (PMID 15083203, 2004). "The diuretic response to these drugs in tumour-bearing (TB) rats may be associated with MMP-9 produced by the tumour cells." (PMID 9792146, 1998). "Moreover, MMP-9—an integral component of NETs—has been implicated in promoting angiogenesis, reinforcing the concept that NETs contribute to the vascular adaptations necessary for tumor progression." (PMID 40365275, 2025). "MMPs (e.g., MMP-2, MMP-9) are involved in extracellular matrix degradation, with their overexpression linked to tumor invasion and metastasis, while TIMPs (e.g., TIMP-1, TIMP-2), as natural inhibitors of MMPs, may exacerbate disease progression when their expression is imbalanced." (PMID 40332776, 2025). "Thus, theoretically, the high specificity and efficacy of CRISPR-Cas9 in blocking MMP-9 expression associated with tumor-specific transfection vectors may minimize the high volume of side effects observed with systemic MMP inhibitors." (PMID 41273852, 2025). "Additionally, MMP‐9 levels were found to be associated with tumor aggressiveness." (PMID 39524138, 2024). "These researchers found that Luteolin caused significant inhibition in tumor growth in cMet-overexpressing patient-derived xenograft models, and immunohistochemistry studies revealed that Luteolin significantly decreased cMet, MMP-9, and Ki-67 expressions in tumor tissues." (PMID 36992138, 2023). "Furthermore, the expression of proteins associated with tumor cell metastasis, including MMP7, MMP9, N-cadherin, vimentin and Snail, was significantly reduced, and the corresponding expression of proteins related to tumor cell apoptosis, such as caspase-3, PPAR and GSK-3β, was strongly increased." (PMID 35348430, 2022).
tumor (continued). "MMP-9 in NETs may also be implicated in NK cell dysfunction resulting in tumor immune evasion." (PMID 36618417, 2022). "Additionally, the anti-angiogenic effect of quercetin has been closely linked to the decrease of VEGF-A, MMP2, and MMP9 expression, as well as to the inhibition of both tumor growth and angiogenesis by targeting VEGFR2 regulated by AKT/mTOR/P70S6K signaling pathway." (PMID 35204240, 2022). "Since MMP-9 is implicated in both early and late processes of tumor progression through the degradation of the extracellular matrix and basement membranes, whether NGAL and MMP-9·NGAL complexes can contribute to tumor progression is worthy of further investigation." (PMID 34327245, 2021). "Additionally, n–3 PUFAs supplementation inhibit cancer progression inducing tumor-associated M2-like macrophages and their CSF-1R, MMP-9 and VEGF expression when compared to n–6 PUFA treatment, and therefore, increased their potential to stimulate angiogenesis." (PMID 34203461, 2021). "Moreover, enhanced MMP-9 expression in CRC cells is associated with increased invasiveness of the tumor, while levels of MMP-2 expression in CRC are lower than in adjacent normal mucosa, and significantly correlate with the depth of invasion and the presence of liver metastasis." (PMID 34071492, 2021). "The neutrophil-released proteases in the tumor microenvironment can facilitate tumor metastasis through the degradation of the extracellular matrix, additionally, there is an association between increased levels of MMP9 and chemotherapy-resistance, which leads to lower survival rates." (PMID 33049964, 2020). "Similarly, MMP-9 participates in tumor-associated tissue remodeling." (PMID 31921385, 2019). "Moreover, Chen and coworkers also demonstrated that the expression of matrix metalloproteinase 9 (MMP9, a typical tumor-associated enzyme) in treated tumors (4T1) could be markedly increased by more than 5-fold after treatment with CA4-NPs." (PMID 31754379, 2019). "Furthermore, accumulated evidence shows that primary tumors can recruit immune cells, such as MMP-9 positive neutrophils, B cells, and M2 polarized macrophages to produce tumor-associated immune cells, which are known to contribute to neovascularization by supplying MMP-9 and other MMPs." (PMID 31921634, 2019). "Additionally, mice deficient in MMP9 are resistant to tumour metastasis." (PMID 29631554, 2018). "Thus, an increase in MMP-9 levels associated with vascular angiogenesis could promote tumour invasion and metastasis." (PMID 30142200, 2018). "Resveratrol is a specific inhibitor of NF-ҡB in different tumor cells; it can downregulate the nuclear localization of NF-ҡB phosphorylation and its acetylation, which cause attenuation of NF-ҡB-regulated gene products (MMP-9, CXCR4) involved in tumor-invasion and metastasis." (PMID 30584449, 2018). "Moreover, MMP-2 and MMP-9 have been associated with tumor progression and decreased survival." (PMID 29713337, 2018). "Furthermore, in vivo studies in MMP-9 deficient mice found that implanting MMP-9 expression in the bone marrow enhanced tumour metastasis, which could facilitate cancer cell migration by promoting angiogenesis." (PMID 29228747, 2017). "In addition, MMP-2 and MMP-9 have been linked to tumor cells migratory and invasive ability." (PMID 28548944, 2017). "Given that vasculogenesis is vital for tumor growth and progression and MMP2 and MMP9 have been implicated in angiogenesis, we next tested whether Rab40b knockdown is required for primary tumor vascularization." (PMID 27789576, 2016). "Except for its well-known function of degrading the extracellular matrix, in vivo studies in MMP-9 deficient mice found that tumor metastasis was enhanced by implanting MMP-9 expression in the bone marrow, which could promote angiogenesis to facilitate cancer cell migration." (PMID 26918342, 2016).
tumor (continued). "Moreover, we evaluated the correlation between tumor stage and MMP-9 expression in twenty-two eligible studies, and the overall results indicate a positive association between high MMP-9 expression and advanced tumor stage (RR = 0.72, 95% CI: 0.63-0.82) with heterogeneity (I2 = 69.8%, p = 0.000)." (PMID 26918342, 2016). "On the basis of our present finding that TSG101 depletion promoted cell invasion and MMP-9 expression in HT1080 cells, but contrarily reduced these events in HeLaS3 cells, TSG101 may be implicated in the invasive potency of tumor cells through regulating the expression of MMP-9." (PMID 26608825, 2015). "The pro-tumor effect of M2 type macrophages is associated with their production of MMPs, urokinase-type plasminogen activator (uPA), uPA receptor (uPAR), and others, of which MMP-9 has been proved to have complex effects, including induction of the angiogenic switch and release of growth factors." (PMID 23527047, 2013). "While major differences in the role of lipocalin-2 on tumor progression and metastasis was observed in these two studies, both confirmed that lipocalin-2 is associated with tumor progression and that complex formation with MMP-9 seems to be part of the mechanism." (PMID 22737251, 2012). "Elevated concentrations of MMP-2 and MMP-9, especially in urine, correlate with the clinical stage and histopathological malignancy of the tumor." (PMID 41977399, 2026). "Kaempferol, a major flavonol widely found in various fruits and vegetables, downregulated the expression of key inflammatory mediators (IL-1β, CXCL8, and MMP9), then reducing neutrophil infiltration and activation while inhibiting tumor growth in CRC." (PMID 41601690, 2026). "In contrast, the high-risk group exhibited stronger co-localization of immunosuppressive tumor-associated macrophages and neutrophils (CD66b+/MMP9+ and CD163+/MMP9+)." (PMID 41491099, 2026). "Immuno-correlation analyses indicated that high MMP9 levels positively correlated with macrophage infiltration and M2 polarization, suggesting a role in tumor immune escape." (PMID 42072446, 2026). "TAMs form a positive feedback loop by secreting TGF‐β and MMP9, further promoting epithelial–mesenchymal transition and driving circulating tumor cells into a highly invasive state that can traverse the vascular wall and establish distant metastases." (PMID 41426206, 2026). "Longitudinal measurement of nanoparticle activation further resolves changes in MMP-9 activity within the tumor in response to therapeutic intervention, illustrating the platform's capacity in monitoring treatment response." (PMID 41675655, 2026). "MMP-9 from tumors facilitates intravasation, while MMPs from CAFs alter the stroma, making it stiffer to help the tumor keep invading." (PMID 41596524, 2026). "Gelatinases, or matrix metalloproteinases (MMP2) and (MMP9) play a pivotal role in tumour matrix degradation, thereby facilitating invasion, angiogenesis and metastasis." (PMID 42121921, 2026). "WEF inhibited colony formation, migration and invasion of tumour cells through the downregulation of MMP‐9 proteolytic activity." (PMID 41546170, 2026). "Conversely, miR-106a-5p promotes MMP-9 expression as well as the migration and invasion of tumor cells." (PMID 40565017, 2025). "MMP-9 is an enzyme that degrades type IV collagen in the basal membrane, acting as a key barrier for tumor and endothelial cells." (PMID 41307829, 2025). "NETs cleave laminin in the niche through neutrophil elastase and MMP9, and the subsequent reorganization of laminin activates the proliferation of dormant tumor cells via integrin α3β1 signaling." (PMID 40027151, 2025). "The elevated MMP-9 activity in our study observed in tumor-adjacent tissue suggests its involvement in tumor invasion through the surrounding stroma." (PMID 40729026, 2025).
tumor (continued). "A key aspect of cancer progression involves the remodeling of the extracellular matrix, a process largely mediated by matrix metalloproteinases (MMPs) such as MMP2 and MMP9, which facilitate tumor invasion and metastasis." (PMID 40136519, 2025). "These compounds have been reported to downregulate the activity and/or expression of MMP-2 and MMP-9, thus potentially suppressing tumor progression." (PMID 40563423, 2025). "Concurrently, NETs release proteolytic enzymes—such as matrix metalloproteinase-9 (MMP-9) and neutrophil elastase—that degrade the extracellular matrix, thereby creating a permissive niche for tumor cell invasion and migration." (PMID 40547026, 2025). "Some works confirmed that the PI3K/AKT regulates numerous pro-angiogenic cytokines, including VEGFA and MMP9, which are involved in tumor angiogenesis." (PMID 40443670, 2025). "Elevated MMP9 levels promote tumor invasion, establishing a feed-forward loop that exacerbates tumor development." (PMID 41305721, 2025). "α-TOS-loaded self-assembled polymer nanoparticles induced intracellular ROS accumulation and endothelial cell apoptosis, reducing MMP-9 expression and inhibiting angiogenesis and tumor invasion in head and neck squamous carcinoma." (PMID 40284474, 2025). "Simultaneously, FN1 activates PI3K/Akt pathways in endothelial cells, upregulating matrix MMP9 expression and promoting vascular wall remodeling, providing channels for tumor cell invasion and metastasis." (PMID 41450464, 2025). "These macrophages lead to increased vascular permeability of tumor cells through the secretion of MMP9, thus aiding in tumor cell metastasis." (PMID 41041337, 2025). "Specifically, MMP-9’s enzymatic breakdown of ECM barriers modulates the tumor microenvironment, facilitating invasion and dissemination." (PMID 41394861, 2025). "GPD1L downregulation represents a hallmark of CRC progression, with affecting the expression of HIF-1α and MMP9 significantly impeding malignant behaviors, nominating it as a candidate tumor suppressor in colorectal neoplasia." (PMID 40538846, 2025). "The study identifies hypoxia-induced exosomal CEACAM5 as a key driver of pancreatic neuroendocrine tumor (pNET) metastasis by promoting tumor-associated macrophage (TAM) M2 polarization and enhancing MMP9 secretion." (PMID 40303340, 2025). "The metalloproteinase MMP-9 was found to be more highly expressed in relapse compared to diagnosis, and also exhibited greater expression in healthy bone marrow compared to tumor tissue, with the latter result having stronger statistical support." (PMID 40427122, 2025). "MMP-9 is significantly overexpressed in GB tumors and plays a pivotal role in disease progression by promoting tumor cell migration and invasion, enhancing angiogenesis, and disrupting the integrity of the blood–brain barrier (BBB)." (PMID 41154699, 2025). "By reducing the expression of M2 macrophage markers (CD163 and CD209) and suppressing the release of tumor-promoting factors such as MMP-9, RANTES, and VEGF, Deoxyschizandrin mitigates the supportive role of TAMs in tumor progression." (PMID 40330466, 2025). "Conversely, the knockout of tumor vascular transient receptor potential vanilloid 4 (TRPV4) upregulates ERK phosphorylation and MMP-9 expression, promoting tumor angiogenesis and metastasis." (PMID 40284474, 2025). "In vivo, FADS1 deletion reduced chemically induced CC/EC tumor burden by 62-75%, accompanied by decreased Ki-67/MMP-9 expression and inflammatory infiltration." (PMID 41102141, 2025). "Grinding tumor tissues and conducting Western blot experiments demonstrated that CuB effectively reduced the protein expression levels of ZFP91, HIF-1α, c-Myc, Cyclin D1, VEGF, and MMP-9 in tumor tissues." (PMID 40860815, 2025). "MMP-9 has been shown to regulate T cell migration and activation, influencing their infiltration and anti-tumor activity." (PMID 39911388, 2025).
tumor (continued). "X Wu reported that downregulation of BMP1 leads to suppression of TGFβ and matrix metalloproteinases 2 (MMP2) and MMP9, and finally decreased tumor invasion in NSCLC." (PMID 39963673, 2025). "MMP9 expression increased with tumor stage and grade, with tumors co-expressing MMP9 and paucimannosidic glycans exhibiting the worst prognosis." (PMID 41041068, 2025). "MMP-9 inhibition has shown significant potential in both reducing the invasiveness of tumor cells and countering immune suppression within the tumor microenvironment." (PMID 40265458, 2025). "The treatment-induced change in the MMP9 was further correlated with the significant reduction in the migration and invasion potential of Myr-NE xenograft-derived tumor cells as compared to Myricetin." (PMID 40552278, 2025). "Prior research has shown that MMP2, MMP3, and MMP9 can modulate the breakdown of nearly all extracellular matrix constituents, hence enhancing tumour motility, invasion, and metastasis." (PMID 39858466, 2025). "Sevoflurane inhibits miR-155 expression and reduces the expression of MMP-2 and MMP-9, which in turn limits tumor cell migratory invasion and induces apoptotic cell death in tumor cells." (PMID 40565017, 2025). "We further investigated the role of MMP9 in facilitating dendritic cell migration in 4MOSC1 tumor-bearing mice treated with tdRT→αPD-1." (PMID 40675962, 2025). "The progression of OSF toward malignancy is associated with the upregulation of SPARC, activation of MMP9, and overexpression of ITGA5, promoting ECM degradation, facilitating cell invasion, and driving tumor progression." (PMID 39865173, 2025). "The regulation of MMP9 expression and activity is thus a critical area of research, with potential therapeutic implications in targeting MMP9 to inhibit tumor progression and manage inflammatory diseases." (PMID 41259376, 2025). "LCN2 is critical for tumor growth, epithelial-to-mesenchymal transition, angiogenesis, and cell proliferation because it forms complexes with matrix metalloproteinase-9 (MMP-9), resulting in the protection of the latter from autodegradation." (PMID 40732340, 2025). "Results from coculture and cell transfer assays suggest that cancer cachexic CD45+ erythroid progenitor cells (EPCs) induce the death of CD34+ progenitor cells and decrease the number of LtβR+, Mmp9+ and Ccl19+ mFbs in tumour‐free mice." (PMID 40665793, 2025). "Mechanistically, capsaicin suppresses EGFR-mediated downstream signaling cascades, including FAK/AkT, PKC/Raf/ERK, and p38 MAPK pathways, as well as AP-1 transcriptional activity, leading to a marked reduction in MMP-9 expression and tumor cell migration." (PMID 40728967, 2025). "Highly expressed MMP2 and MMP9 can widely degrade various proteins on tumor cell membranes and have become important targets in the field of cancer treatment." (PMID 40563539, 2025). "The concentrations of MMP-9, similarly to those of the classical tumor markers (CA 19-9 and CEA), were significantly higher in the sera of CRC patients in comparison to healthy subjects." (PMID 40725774, 2025). "Concomitantly, expression of established M2 markers CCL20 and MMP9 increased during this differentiation, confirming the predominant M2 phenotype of tumor-infiltrating macrophages." (PMID 41346635, 2025). "In the tumor environment, the MMP-9-mediated hydrolysis of the hydrophilic peptide exposed and retained the hydrophobic fragment in the 4T1 tumor." (PMID 40284474, 2025). "EMT-inducing transcription factors, such as TWIST1 and SNAIL1, not only repress E-cadherin but also drive tumor angiogenesis through the regulation of MMP9, N-cadherin, and vimentin." (PMID 40647432, 2025). "In mechanism, we found that MIDN interacted with the CTNNB1/MMP9 axis, which was verified as an important pathway in suppressing the tumour immune microenvironment." (PMID 40111059, 2025).